FBN1 (fibrillin 1)
Diseases named in the same sentence as FBN1 in open-access papers (continued):
Sharing a sentence is not in itself a finding about the gene and the disease.
Duchenne muscular dystrophy (2 papers, 2020 to 2024). Duchenne muscular dystrophy (DMD) is a neuromuscular disease characterized by rapidly progressive muscle weakness and wasting due to degeneration of skeletal, smooth and cardiac muscle. "COL1A2, FBN1 and FN1 may be novel biomarkers for DMD, and the siRNAs designed in our study were help to develop adjunctive therapy for Duchenne muscular dystrophy." (PMID 38762732, 2024).
endometrial cancer (2 papers, 2020 to 2025). Primary or metastatic malignant neoplasm involving the endometrium (mucous membrane that lines the endometrial cavity). "By controlling the autophagy signaling system and cell cycle and functioning as an E3 ligase that ubiquitin-dependently degrades Fibrillin-1 (FBN1), FBXO2 has been shown to stimulate the growth of endometrial cancer." (PMID 41035649, 2025).
endometriosis (2 papers, 2020 to 2024). The growth of functional endometrial tissue in anatomic sites outside the uterine body. "Notably, fibrillin (FBN1), was the only gene to show differential expression between the normal and endometriosis groups at day 6 of decidualization." (PMID 38402336, 2024). "Compared to decidualized cells from normal donors, FBN1 expression was elevated (2.09-fold, FDR < 0.0001) in the decidualized cells of donors with endometriosis." (PMID 38402336, 2024).
germ cell tumor (2 papers, 2016 to 2020). A benign or malignant, gonadal or extragonadal neoplasm that originates from germ cells. "A previous study reported that FBN1 overexpression plays a key role in the development of germ cell tumors." (PMID 32934754, 2020). "Our data suggest, that progression of GCNIS to overt germ cell tumour is connected with a decrease of FBN-1 production." (PMID 27487789, 2016). "PARP1 regulates FBN1 gene expression through Sp1 and these data suggest, that increased PARP expression in neoplastic cells in germ cell tumours can lead to increased FBN1 gene expression." (PMID 27487789, 2016). "In conclusion, in this translational study we showed for the first time that FBN-1 is overexpressed in TGCTs and especially in GCNIS when compared to non-neoplastic testicular tissue in patients with germ cell tumors." (PMID 27487789, 2016). "FBN-1 is overexpressed in TGCTs and especially in GCNIS when compared to non-neoplastic testicular tissue in patients with germ cell tumors and could be involved in germ cell neoplasia in situ development." (PMID 27487789, 2016).
gestational diabetes (2 papers, 2025). Carbohydrate intolerance first diagnosed during pregnancy. "This study elucidates a novel correlative association between gestational diabetes mellitus (GDM) and maternal behavioral deficits, accompanied by altered FBN1 gene expression, elevated TNF-α, and disrupted serotonin signaling in the prefrontal cortex (PFC)." (PMID 41399726, 2025). "This study provides novel evidence that gestational diabetes mellitus induces significant neurobiological alterations in the maternal prefrontal cortex, characterized by overexpression of the FBN1 gene, elevated TNF-α levels, and decreased serotonin concentrations in the prefrontal cortex." (PMID 41399726, 2025).
heart abnormality (2 papers, 2016 to 2020). "A bicuspid aortic valve (BAV) is a common congenital heart abnormality that appears to be associated with mutations in FBN1 because of the significantly higher frequency of these mutations in affected patients relative to the general population." (PMID 27138491, 2016).
mesothelioma (2 papers, 2018 to 2019). A usually malignant and aggressive neoplasm of the mesothelium which is often associated with exposure to asbestos. "Fibrillin-2 is upregulated in mesothelioma and localises gremlin-1 to the tumour microenvironment where it binds fibrillin-1 and -2 and colocalises with microfibrils in cells and mesothelioma tumours." (PMID 30016650, 2019). "We have previously shown high expression of FBN1 and FBN2 as well as MMP2 in association with high GREM1 expression in JP5 cells as well as in other mesothelioma cells." (PMID 29968778, 2018).
Microspherophakia (2 papers, 2016 to 2018). Microspherophakia is a rare congenital anomaly characterized by the abnormal spherical shape of the crystalline lens. "Because the interaction between the LTBP2 and the Fibrillin-1 proteins is close to this LTBP2 C-terminal region, we could speculate that the instability of the zonular fibers characteristic in microspherophakia is due to the loss of the association between these two proteins." (PMID 29751740, 2018).
Myhre syndrome (2 papers, 2019 to 2023). Myhre syndrome is characterized by striking muscular build, short stature, reduced joint mobility, brachydactyly, mixed hearing loss and mental retardation of variable severity. "Moreover, we previously found that inclusions are also present in fibroblasts of GPHYSD patients carrying FBN1 mutations and Myhre syndrome (MIM139210) patients carrying SMAD4 mutations, suggesting that a common pathway is responsible for the formation of such inclusions." (PMID 31516831, 2019).
Primary cardiomyopathy (2 papers, 2020 to 2025). "Primary cardiomyopathy in MFS may stem from intrinsic myocardial dysfunction associated with FBN1 mutations and abnormal TGF-β signaling." (PMID 40416127, 2025).
Stickler syndrome (2 papers, 2023 to 2024). Stickler syndrome is an inherited vitreoretinopathy characterized by the association of ocular signs with more or less complete forms of Pierre-Robin sequence, bone disorders, and sensorineural deafness (10% of cases). "Exome sequencing identified 21 potential pathogenic variants of 13 genes in 20 of 75 (26.7%) probands, including genes for Stickler syndrome (COL11A1 and COL2A1; 6/20), FEVR (FZD4, LRP5, and TSPAN12; 5/20), and others (FBN1, GPR179, ZEB2, PAX6, GPR143, OPN1LW, FRMD7, and CACNA1F; 9/20)." (PMID 38243264, 2024).
tricuspid valve prolapse (2 papers, 2015 to 2020). Abnormal protrusion of one or more of the leaflets of tricuspid valve into the right atrium during systole. "Patients with FBN1 variants affecting a cysteine residue showed a higher rate of SV dilatation (p = 0.033) and tricuspid valve prolapse (p = 0.03) than patients with variants not involving a cysteine residue." (PMID 32679894, 2020).
adolescent idiopathic scoliosis (1 paper, 2022). A scoliosis with no known cause arising in adolescent. "Fibrillin-1 (FBN1) is an extracellular matrix glycoprotein essential to the structural component of microfibrils and FBN1 gene polymorphisms can be associated with adolescent idiopathic scoliosis (AIS) susceptibility." (PMID 35526034, 2022).
aortic disorder (1 paper, 2023). Pathology involving the thoracic, thoracoabdominal, or abdominal aorta (including aneurysms). "Except for two in FBN1, the P/LP variants were associated with only isolated aortic disorders." (PMID 37644562, 2023).
behavioral disorders (1 paper, 2022). "Literature on the relation between the FBN1 gene and behavioral disorders is limited." (PMID 35462799, 2022).
brain ischemia (1 paper, 2022). Diminished or absent blood supply to the brain caused by obstruction (thrombosis or embolism) of an artery resulting in neurologic damage. "While TGFbeta has been associated with neuroinflammatory pathways and identified as neuroprotective following brain ischemia, genes in subgroup ‘h’ include NNROS and FBN1 which are associated with negative regulation of the TGFbeta signalling pathway." (PMID 35857765, 2022).
breast tumor (1 paper, 2024). "The online TNMplot gene expression analysis presented significant upregulation of the FBN1 gene when comparing normal breast tissue to breast tumor gene chip data." (PMID 39273393, 2024).
choriocarcinoma (1 paper, 2016). An aggressive malignant tumor arising from trophoblastic cells. "Fibrillin-1 expression was detected in 85 (86.7 %) of seminomas, 78 (83.0 %) of embryonal carcinomas, 21 (95.5 %) of yolk sac tumors, 3 (17.6 %) of choriocarcinomas, 35 (71.4 %) of teratomas, 68 (97.1 %) of GCNIS and 1 (1.2 %) non-neoplastic tissue." (PMID 27487789, 2016). "Expression of FBN-1 in all subtypes of TGCTs (seminoma, embryonal carcinoma, yolk sac tumour, teratoma, choriocarcinoma) was significantly lower in comparison to the expression in GCNIS." (PMID 27487789, 2016). "Among TGCTs, the highest expression was observed in seminomas and the lowest in choriocarcinoma, suggesting a decrease of FBN-1 expression with the process of differentiation." (PMID 27487789, 2016).
Cirrhosis (1 paper, 2024). A chronic disorder of the liver in which liver tissue becomes scarred and is partially replaced by regenerative nodules and fibrotic tissue resulting in loss of liver function. "ADAMTSL4 is a secreted glycoprotein that contributes to ECM homeostasis, and was previously demonstrated to induce fibrillin-1 deposition in cirrhosis." (PMID 38603681, 2024).
colorectal tumors (1 paper, 2015). "In our previous studies, we have proved that the promoters of FBN1 gene are frequently hypermethylated in patients with colorectal tumors and can be detected in their stool samples." (PMID 25802477, 2015).
congestive heart failure (1 paper, 2023). Failure of the heart to pump a sufficient amount of blood to meet the needs of the body tissues, resulting in tissue congestion and edema. "In the same line, Fibrillin 1 upregulation has been reported in the context of cardiac remodeling by ventricular tachypacing in a congestive heart failure canine model and is associated with cardiac fibrosis." (PMID 37507917, 2023).
Corneal astigmatism (1 paper, 2018). "It has also been proposed that defects in the FBN1 gene might affect the zonule and corneal connective tissues, resulting in greater corneal astigmatism." (PMID 29854424, 2018).
coronary artery diseases (1 paper, 2020). "The different FBN1 genotypes have been studied in several populations, and the frequencies of these genotypes in our present study are in accordance with what others have reported previously among healthy subjects, AAA-patients, patients with coronary artery diseases and middle-aged subjects." (PMID 32303188, 2020).
craniostenosis (1 paper, 2012). "As found in our patient, when the deletion involves other genes besides FBN1, other unusual features can be found, such as those described here (craniostenosis, hypothyroidism and intellectual deficit)." (PMID 22260333, 2012).
cutaneous vasculitis (1 paper, 2023). Inflammation of the blood vessel wall characterized by palpable purpura. "Here we report an FBN1 variant in a child with an unusual skin rash mimicking cutaneous vasculitis, and mild aortic root dilatation." (PMID 37397156, 2023).
cutis laxa (1 paper, 2023). Cutis laxa (CL) is an inherited or acquired connective tissue disorder characterized by wrinkled, redundant and sagging inelastic skin associated with skeletal and developmental anomalies and, in some cases, with severe systemic involvement. "Missense substitutions leading to improper secretion of FBLN5 and reduced interaction with elastin and fibrillin-1 have been reported in recessive cutis laxa." (PMID 36794549, 2023).
dislocation (1 paper, 2013). A displacement of a part (especially a bone) from its normal position. "The rather severe cardiovascular and skeletal system phenotypes with less occurrence of lens dislocation observed in the MF1 family were linked to a PTC mutation (c.813C>A) of the FBN1 gene." (PMID 23592911, 2013).
Epiretinal membrane (1 paper, 2021). An epiretinal membrane is a thin sheet of fibrous tissue on the surface of the retina along the inner limiting membrane. "BS, BPM, and VC specimens were selectively collected in macular hole and epiretinal membrane patients during vitrectomy and were then immunostained with antibodies for podoplanin, LYVE-1, and fibrillin-1 and -2." (PMID 33669860, 2021).
exfoliation syndrome (1 paper, 2021). An autosomal dominant disorder caused by mutations in the LOXL1 gene, encoding lysyl oxidase homolog 1. "For example, a large-scale GWAS study found that LOXL1 variants can increase the deposition of elastin and fibrillin-1 that stabilizes the ECM, thereby protecting against exfoliation syndrome." (PMID 34393991, 2021).
Fibroadenoma (1 paper, 2020). A benign tumor of the breast characterized by the presence of stromal and epithelial elements. "We detected an increase in the expression of six proteins (NUDT19, FBN1, NONO, FLNA, SCPEP1, and galactosidase alpha) in fibroadenoma." (PMID 33194682, 2020).
gallbladder cancer (1 paper, 2024). "A comparative analysis of differential proteomic data revealed 7 hypermethylated or down-regulated genes (e.g., FBN1, LPP, SOD3) and 61 hypomethylated or up-regulated genes (e.g., HBE1, SNRPF, TPD52), which contributed to the early diagnosis of gallbladder cancer." (PMID 38427106, 2024).
growth disorders (1 paper, 2023). "All these variants were identified in genes already associated with growth disorders: PROKR2 (N = 2), PTPN11 (N = 6), ANKRD11 (N = 1), NPR2 (N = 1), NF1 (N = 1), ACAN (N = 1), GH1 (N = 1), FBN1 (N = 1), COMP (N = 1), IGF1R (N = 1), ARID1A (N = 1), and CASR (N = 1)." (PMID 37605180, 2023).
hepatocellular adenoma (1 paper, 2004). A benign epithelial neoplasm arising from the hepatocytes. "In hepatocellular adenoma, another benign condition of hepatocytic proliferation associated with an irregular and abnormal vascularization, both elastin and fibrillin-1 immunostaining pointed to the great number of vascular sections distributed inside the tumor." (PMID 14960209, 2004). "Immunohistochemical studies for fibrillin-1 and elastin were performed on unfixed cryostat sections of focal nodular hyperplasia (22 cases), hepatocellular adenoma (15 cases) and surrounding liver (34 cases)." (PMID 14960209, 2004). "The different patterns of fibrillin-1 in hepatocellular adenoma could account for the heterogeneity of the arterial vascularization in this tumor characterized by frequent necrotico-hemorrhagic changes." (PMID 14960209, 2004). "In hepatocellular adenoma, the different patterns of fibrillin-1 could be related to the heterogeneity of the arterial vascularization and to the frequent necrotico-hemorrhagic changes." (PMID 14960209, 2004). "Therefore, in this work, the expression and distribution of fibrillin-1 and elastin were studied in hepatic focal nodular hyperplasia and compared with surrounding liver and hepatocellular adenoma." (PMID 14960209, 2004). "The different patterns of fibrillin-1 expression in FNH and hepatocellular adenoma, in comparison with normal liver, could be a reflection of the response." (PMID 14960209, 2004).
hydrops fetalis (1 paper, 2024). Hydrops fetalis is a severe and challenging fetal condition usually defined as the excessive accumulation of fetal fluid within the fetal extravascular compartments and body cavities that manifests as edema, pleural and pericardial effusion and ascites. "The genetic etiology of hydrops fetalis in rabbits and dogs is yet to be determined; however, a CRISPR-Cas9 experiment utilizing a 5-base pair (bp) deletion in the FBN1 gene has resulted in piglets with hydrops fetalis phenotypes." (PMID 39409761, 2024).
Hyperglycemia (1 paper, 2025). An increased concentration of glucose in the blood. "Therefore, we cannot definitively rule out that the prefrontal neurochemical changes are solely due to persistent hyperglycemia versus other metabolic factors, nor can we directly correlate peripheral asprosin with central FBN1 expression." (PMID 41399726, 2025).
hypothyroidism (1 paper, 2012). Abnormally low levels of thyroid hormone. "Her deletion comprises 19 genes and predicted genes including FBN1, besides SEMA6D and COPS2 that may have contributed to the intellectual deficit and hypothyroidism, respectively." (PMID 22260333, 2012).
Incisional hernia (1 paper, 2013). An abdominal hernia that occurs at a site of weakness in the abdominal wall resulting from an incompletely-healed surgical wound. "They found that FBN1 may be an important contributing factor to tissue stability and incisional hernia formation." (PMID 22648066, 2013).
keratoconus (1 paper, 2017). A degenerative, structural disorder of the eye, characterized by a cone-shaped protrusion of the cornea. "Therefore, findings from this current study showing increased IFS and thinner corneas in fibrillin-1–deficient animals are consistent with findings observed in keratoconus, suggesting that similar biochemical mechanisms may be active." (PMID 28395026, 2017).
mental disorder (1 paper, 2021). A disease that has its basis in the disruption of mental process. "The FBN1 gene is a strong candidate for probable MDD, as this gene has been previously implicated in mental disorders." (PMID 34202750, 2021).
mixed connective tissue disease (1 paper, 2005). Mixed connective tissue disease (MCTD) is a rare autoimmune disorder that is characterized by features commonly seen in three different connective tissue disorders: systemic lupus erythematosus, scleroderma, and polymyositis. "Recently, the presence of autoantibodies against the same recombinant fibrillin-1 fragment has also been shown for sera from patients with SSc, localized scleroderma, mixed connective tissue disease and primary pulmonary hypertension syndrome." (PMID 16277674, 2005).
non-compaction cardiomyopathy (1 paper, 2020). Left ventricular non-compaction (LVNC) is characterized by prominent left ventricular trabeculae and deep inter-trabecular recesses. "Histological analysis of the myocardial tissue showed a highly reduced fibrillin-1 deposition associated with a decreased compaction of the myocardial tissue (resembling LV non-compaction cardiomyopathy (LVNC)), which deteriorated with age in MFS mice compared to WT mice." (PMID 32987703, 2020).
open-angle glaucoma (1 paper, 2024). Chronic outflow obstruction of the eye's drainage canals that can lead to increased internal eye pressure and optic nerve damage. "For example, open angle glaucoma presentations are associated with mutations of fibrillin-1, ADAMTS10 (a disintegrin and metalloproteinase with thrombospondin motifs-10) and LTBP2 (latent transforming growth factor β binding protein-2) that are different proteins involved in regulating microfibrils." (PMID 38347040, 2024).
pancreatic cancer (1 paper, 2020). "In addition, three hub genes (SPARC, COL6A3, and FBN1) may also play a vital role in the microenvironment of pancreatic cancer through the regulation of tumor-infiltrating immune cells, suggesting they could serve as potential therapeutic targets for the modulation of the antitumor immune response." (PMID 32934754, 2020). "The role of FBN1 in the development of pancreatic cancer and its correlation with the prognosis of patients has not been reported previously." (PMID 32934754, 2020).
Pierson syndrome (1 paper, 2025). Pierson syndrome is characterized by the association of congenital nephrotic syndrome and ocular anomalies with microcoria. "The causative genes linked to the Knobloch, Marfan, and Pierson syndromes are COL18A1, FBN1, and LAMB2, respectively." (PMID 40725504, 2025).
pigmentary glaucoma (1 paper, 2013). Pigmentary glaucoma is a type of secondary open-angle glaucoma characterized by heavy homogenous pigmentation of the trabecular meshwork, iris transillumination defects, and pigment along the corneal endothelium (Krukenberg spindle). "However, the inability to perform ocular examination on other affected family members limits the establishment of a causal relationship between pigmentary glaucoma and the specific FBN1 mutation identified in our patient." (PMID 23444230, 2013).